AQP3 (aquaporin 3 (Gill blood group))
Diseases named in the same sentence as AQP3 in open-access papers (continued):
Sharing a sentence is not in itself a finding about the gene and the disease.
thyroid tumor (1 paper, 2012). A benign or malignant neoplasm affecting the thyroid gland. "From this point of view, it is conceivable that the expression of AQP3 and/or AQP4 may contribute the biological behavior of thyroid tumors." (PMID 22808259, 2012). "In conclusion, our findings suggest that the differential expressions of AQP3 and AQP4 may reflect the biological nature and/or function of normal, hyperplastic, and neoplastic thyroid cells and, additionally, have some value for diagnosing thyroid tumors." (PMID 22808259, 2012). "The differential expressions of AQP3 and AQP4 may reflect the biological nature and/or function of normal, hyperplastic, and neoplastic thyroid cells and additionally may have value in determining differential diagnoses of thyroid tumors." (PMID 22808259, 2012).
type 1 diabetes (1 paper, 2021). "The results showed that the expression level of AQP3 in the skin was reduced in type 1 diabetes, which may be one of the factors that cause xeroderma." (PMID 33494453, 2021). "We previously found that the expression level of AQP3 in the skin of model mice with STZ-induced type 1 diabetes was significantly decreased when the skin was dry." (PMID 33494453, 2021). "In model mice with STZ-induced type 1 diabetes, in which a decrease in skin AQP3 was observed, both the blood TNF-α concentration and cutaneous TNF-α expression were increased." (PMID 33494453, 2021). "We previously analyzed the role of cutaneous AQP3 in the development of diabetic xerosis using streptozotocin (STZ)-induced type 1 diabetes model mice." (PMID 33494453, 2021).
undifferentiated thyroid carcinoma (1 paper, 2012). "We should also consider the possibility of other AQPs in undifferentiated thyroid carcinoma in which neither AQP3 nor AQP4 was expressed." (PMID 22808259, 2012).
uremia (1 paper, 2022). A clinical syndrome associated with the retention of renal waste products or uremic toxins in the blood. "Although uremia, glucose and insulin have been found to affect AQP3 gene expression, most studies have been performed in vitro." (PMID 36038817, 2022).
cancer (108 papers, 2005 to 2026). A tumor composed of atypical neoplastic, often pleomorphic cells that invade other tissues. "Changes in aquaporin (AQP) expression, associated with CSCs and cancer cell migration, was assessed by immunodetection and RT‐qPCR, indicating a decrease in AQP3, AQP5 and AQP6 gene and protein expression upon DM treatment." (PMID 41318947, 2026). "Recent reports have implicated many aquaporins in cancer, and mounting evidence shows that AQP3 is crucial for cancer development and metastasis." (PMID 38336645, 2024). "AQP3 is the most frequently cancer-associated aquaporin, being abnormally expressed in different types of cancers, such as lung, skin, colon, pancreatic, gastric, and liver." (PMID 39125952, 2024). "Aquaporin 3 (AQP3), a water channel protein, has recently been found to play a critical role in cancer-associated inflammation." (PMID 38463942, 2024). "Aquaporins have been associated with cancer invasion, and metastasis and, in particular, AQP3 seems to affect cellular functions commonly associated with cancer progression, including proliferation, migration and metastasis." (PMID 36983077, 2023). "The expression patterns and subcellular localization of AQP3 are specific to different cell types and have been associated with cancer cell aggressiveness and mobility." (PMID 38136293, 2023). "The results of Bioinformatics revealed that AQP3 was positively associated with several cancer-related pathways." (PMID 35957833, 2022). "AQP3 expression affected cellular functions commonly associated with cancer progression, including proliferation, motility, and EMT." (PMID 28991174, 2017). "The results showed that elevated expression of AQP3 in cancer tissues was associated with the Lauren classification (P = 0.034), lymph node metastasis (P = 0.006), and lymphovascular invasion (P = 0.024)." (PMID 26918728, 2016). "Because EMT of tumor cells is accepted to be closely associated with cancer invasion and metastasis, we investigated the effects of AQP3 on GC cell proliferation, migration, and invasion using EdU incorporation assays and transwell assays." (PMID 24887009, 2014). "The aberrant expression of AQP3, a key molecule in cancer therapy, has been reported to be associated with various cancer-related processes, including cell proliferation, invasion, migration, and apoptosis, in various cancers." (PMID 38051132, 2024). "Interestingly, high AQP3 expression has been associated with other types of cancers, including for example colorectal carcinoma, pancreatic ductal carcinoma, hepatocellular carcinoma, lung cancer, and gastric adenocarcinoma." (PMID 30042691, 2018). "Abnormal expression of AQP3 may be associated with different diseases including cancer." (PMID 35874817, 2022). "Moreover, a few studies have directly implicated AQP3 in EMT progression in cancer cells." (PMID 28991174, 2017). "Collectively, these findings position AQP3 as a key driver of cancer progression and stemness through distinct signalling mechanisms." (PMID 40806720, 2025). "Aquaporin 3 (AQP3) is a protein found in tissues like the skin, respiratory tract, kidney, and certain cancers." (PMID 41393785, 2025). "AQP3 expression levels are increased with cancer development from the early to late stages of the tumor, while AQP5 expression is augmented in the early stage but almost undetectable in later stages, showing its potential as a biomarker of this disease." (PMID 39941100, 2025). "In several tumors, AQP3 expression was correlated with the activation of signaling pathways that promote cancer cell proliferation, migration and invasion." (PMID 39941100, 2025).
cancer (continued). "Based on these findings, emerging evidence revealed that abnormal expression and functions of AQP3 are related to the onset of numerous diseases including diarrhea, constipation, intestinal oxidative stress, and cancer." (PMID 39857360, 2024). "Recent evidence has shown that AQP3 is involved in cancer progression and metastasis by modulating intracellular signaling that alters cellular responses." (PMID 39857360, 2024). "AQP3 has been studied to influence cancer progression by transporting H2O2 and regulating intracellular ROS levels." (PMID 38230207, 2024). "AQP3 serves a crucial function in cancer biology because it modifies cellular signaling; downstream protein expression patterns, promotes tumour formation, and facilitates cellular proliferation." (PMID 38336645, 2024). "In the present study, we have systematically investigated the clinical relevance and anti-cancer efficacy of AQP3 in LUAD microenvironment in vitro and in vivo." (PMID 39060229, 2024). "The organogold compound also revealed a potent inhibitory effect on AQP3 activity, a member of the AQP family closely associated with cancer biological functions and aberrantly expressed in several human cancers." (PMID 39771545, 2024). "Accordingly, selective inhibition of AQP3 reduced cell viability and retarded cancer progression, possibly degrading its transport abilities." (PMID 39857360, 2024). "Multiple studies have shown that AQP3 promotes cancer progression by increasing the motility and invasiveness of cancer cells." (PMID 38230207, 2024). "H-score was used to quantify the staining by ImageJ IHC Profiler, and the results showed that the AQP3 expression level in cancer tissues was significantly higher than in adjacent tissues (n = 100)." (PMID 39060229, 2024). "The expression of AQP3 in gastric cells is primarily controlled by the ERK signaling pathway, and reduction of AQP3 can inhibit the proliferation and migration of cancer cells generated by H. pylori." (PMID 37215092, 2023). "Among the AQP-targeted drugs reported so far, metallodrugs demonstrated potent AQP3 inhibition suggesting a great potential for cancer treatment." (PMID 36983077, 2023). "Increasing evidence suggests that the water/glycerol channel aquaporin-3 (AQP3) plays a key role in cancer and metastasis." (PMID 36983077, 2023). "The high expression of AQP3 has been observed in several cancers, which promotes to metastasis, proliferation, and epithelial-to-mesenchymal transition (EMT)." (PMID 37334171, 2023). "AQP3 is also expressed in many cancer tissues and cells, but its expression patterns differ from those of cancers." (PMID 35972604, 2022). "Aquaporins (AQPs), such as aquaporin-3 (AQP3), which play crucial roles in cell apoptosis, proliferation, and migration, have been proposed as new drug targets for cancer treatment." (PMID 36176441, 2022). "We propose CAP as a 'selective' onco-therapeutic against cancer stemness, with the AQP3/FOXO1 axis being one molecular mechanism." (PMID 35637961, 2022). "In a nutshell, the integration of biomechanical and bioimaging tools allow to infer the biological behavior of these cancer cells, suggesting AQP3- and AQP5-targeting as a promising strategy for anticancer therapy." (PMID 35455986, 2022). "AQP3 also plays a key role in cancer progression in cells and tumors derived from several cancer subtypes." (PMID 36212456, 2022). "P2W18, a polyoxotungstate, showed the ability to suppress cancer cell migration mainly by affecting AQP3, implying the potential of AQP3 as an anticancer agent in tumors with high AQP3 expression." (PMID 35972604, 2022). "Similar results have been reported on the reduced proliferation of cancer cell lines by silencing the peroxiporins AQP3, AQP5, and AQP8." (PMID 35741021, 2022). "Recently, AQP3 has been shown to express in various cancer cells including multiple cancer tissues from stomach, colon, and lung." (PMID 35820920, 2022).
cancer (continued). "Among these 330 commonly predicted genes, AQP3, one member of the aquaporins family which acted as onto-promoters in diverse cancer types, attracted our attention." (PMID 35957833, 2022). "The intrinsic pathway of CD133+Huh7 cells is regulated by the AQP3 protein in the progression and metastasis of several malignant tumors." (PMID 35820920, 2022). "Here, we summarize the upstream regulators and the downstream activated tumor-related signaling pathways of AQP3 in different cancers, hoping to provide some basis for AQP3 as a target for cancer treatment (for more details)." (PMID 35972604, 2022). "Briefly, the high expression of seven blood group antigen genes, i.e., FUT7, AQP1, P1, C4A, AQP3, KEL, and DARC, was significantly associated with good prognosis in six types of cancers, i.e., KIRC, HNSC, LUAD, CESC, SARC, MESO." (PMID 35955933, 2022). "Expression of vimentin and fibronectin have also been found to be positively correlated with AQP3 expression, whereas E-cadherin expression has been shown to be significantly reduced among cancer cells with enhanced AQP3 expression." (PMID 35847914, 2022). "It is widely accepted that AQP3 contributes to the high glycerol and ATP supply for cancer cells required for cell growth maintenance." (PMID 35252273, 2022). "There are many transcription factors, cytokines, microRNAs, and other regulators that affect AQP3 in cancer." (PMID 35972604, 2022). "Accordingly, most of the miRNAs described until now as AQP3 modulators exert their beneficial effects in cancer cells by attenuating their growth and metastasis throughout the body." (PMID 35187089, 2022). "Through whole transcriptome sequencing followed by assays in vitro, in vivo and using clinical samples, we propose CAP as a promising onco-therapy targeting cancer stemness via the AQP3/FOXO1 axis." (PMID 35637961, 2022). "Noteworthy, AQP3 high expression levels have been reported for different types of cancer, including skin, breast, and pancreatic cancer, with demonstrated impact on cell migration and proliferation." (PMID 35455986, 2022). "AQP3 functions as a functional protein molecule, and knockdown of AQP3 inhibits cancer cell proliferation, invasion, and migration as well as promotes apoptosis." (PMID 35972604, 2022). "In this series, a gold(III) complex [Au(phen)Cl2]Cl (Auphen, phen = 1, 10-phenanthroline) was found to decrease cell proliferation in AQP3-expressing cells, revealing its potential for the treatment of carcinomas with large AQP3 expression." (PMID 35187089, 2022). "Expression patterns when SFN was applied in an encapsulated form showed a reduction of cancer markers and an increase of AQP3." (PMID 34714214, 2021). "Overexpression and ectopic expression of AQP3 have been observed in several cancers, where it has been shown to induce metastasis, proliferation, and epithelial-to-mesenchymal transition (EMT)." (PMID 34512326, 2021). "These properties strongly indicated that AQP3 functions not only as a biomarker in several cancers but is also a potential gatekeeper in IM." (PMID 34512326, 2021). "Regarding HIF-1α mRNA expression, the pattern appeared more similar to that of AQP3 protein expression, which follows what has been described in the literature for cancer cells." (PMID 33917751, 2021). "Hypoxia-inducible factors (HIFs) appear to induce AQP3 in cancer and, conversely, the aquaglyceroporin also stabilizes the hypoxic factors, the expression of the two is inversely correlated in healthy cells." (PMID 33917751, 2021). "In cultured cancer cells, increased AQP3 expression increases cell proliferation, migration, and invasion, playing a pivotal and complex role in cancer progression." (PMID 34267676, 2021). "In biopsies from patients with different stage EC cancers, AQP3 protein expression was correlated with histological grade." (PMID 33499000, 2021).
cancer (continued). "While AQP3 is upregulated in cancer cells, in response to low oxygen levels, healthy cells decrease their expression under hypoxia." (PMID 33917751, 2021). "Our data show that the solution of the P2W18 strongly affects AQP3 activity and cancer cell growth, unveiling its potential as an anticancer drug against tumors where AQP3 is highly expressed." (PMID 32252345, 2020). "Among all the identified AQP isoforms, AQP1 (expressed in endothelial cells) and AQP3 (expressed in the basal layer of keratinocytes in human skin) are of particular interest for the study of cancer model." (PMID 32351935, 2020). "Since cancer cells have elevated levels of H2O2, AQP3-mediated H2O2 transport plays an important role in the development of cancer." (PMID 32351935, 2020). "In this regard, AQP-targeted drugs are believed to have great potential in treating cancer, where metallic compounds are considered the most potent AQP3 inhibitors." (PMID 32252345, 2020). "This shows that AQP3 can not only regulate cell proliferation in cancer cells, but also in intramuscular preadipocytes." (PMID 32331274, 2020). "Altogether, our data revealed that P2W18 strongly affects AQP3 activity and cancer cell growth, unveiling its potential as an anticancer drug against tumors where AQP3 is highly expressed." (PMID 32252345, 2020). "AQP3 is related to wound healing, lipid metabolism, and regulation of the proliferation and differentiation of several cancer cell types." (PMID 32252345, 2020). "In summary, in cultured cancer cells and the corresponding cancer tissues, increased AQP3 expression stimulates a variety of intracellular signalling pathways, leading to cell proliferation, migration, invasion and EMT." (PMID 32662230, 2020). "The expression level of AQP3 was found to correlate with cancer cell migration through a mechanism involving its hydrogen peroxide transport function." (PMID 31277235, 2019). "In other types of cancers, AQP3, AQP4, or AQP5 are increased in expression and influence viability, proliferation and migration." (PMID 31477744, 2019). "AQP3-mediated H2O2 transport has been linked to cancer cell migration, explaining its overexpression in cancer tissues." (PMID 31277235, 2019). "Many reports suggest the existence of a possible relationship between AQP3 expression and cancer progression or prognosis in many neoplastic tissues." (PMID 30893772, 2019). "The potential beneficial use of AQP3 inhibitors or modulators (decreasing AQP3 expression) remains to be evaluated for cancer treatment." (PMID 30042691, 2018). "Human HSC AQP3 was suggested to interact with the PNPLA3 I148M variant in causing hepatic steatosis, NASH, fibrosis and cancer." (PMID 30042691, 2018). "Most research on the function of AQP3 has focused on cancer, and few studies regarding the relationship between AQP3 and human reproduction have been published." (PMID 30285121, 2018). "In cultured cancer cells, increased AQP3 expression stimulated several intracellular signaling pathways and resulted in increased cell proliferation, migration, and invasion as well as aggravation of epithelial-to-mesenchymal transition." (PMID 28991174, 2017). "This review article will expand our understanding of the known pathophysiological findings regarding AQP3 in cancer." (PMID 28991174, 2017). "Epidermal growth factor (EGF) and estrogen both contribute to cancer development and have been suggested as upstream regulators of AQP3 expression." (PMID 28991174, 2017). "Recently, implication of several aquaporins in cancer has been reported and increasing evidence strongly suggests that AQP3 plays a pivotal role in cancer progression and metastasis." (PMID 28991174, 2017). "Here, we give a thorough review of current knowledge regarding AQP3 expression in cancer and how AQP3 contributes to cancer progression via signaling that modulates cellular mechanisms." (PMID 28991174, 2017).